ATPAF1 (ATP synthase mitochondrial F1 complex assembly factor 1)
Description:
Has a complex stabilizing activity in the assembly of the mitochondrial F1-F0 complex.
Synonyms: ATP11; FLJ22351; Atp11p
Tractability: Antibody: UniProt places it where antibodies can reach, with medium confidence. PROTAC: ubiquitination databases record sites on it; its protein half-life has been measured.
Gene: Protein-coding gene on chromosome 1 (46,632,071 to 46,673,867, reverse strand). Ensembl gene ENSG00000123472.
Subcellular location: Mitochondrion inner membrane
Subcellular location (Human Protein Atlas): Mitochondria
Gene Ontology:
Molecular function: protein binding; protein-containing complex stabilizing activity
Biological process: mitochondrial proton-transporting ATP synthase complex assembly; protein-containing complex assembly
Cellular component: mitochondrion; mitochondrial inner membrane
Genetic constraint (gnomAD): Loss-of-function variants: 21 observed, 35.26 expected, observed/expected ratio (o/e) 0.6, 90% interval 0.42 to 0.86. The upper end of that interval is the gene's LOEUF score, 0.86, which puts it in group 3 of 6, group 1 being the genes least tolerant of losing a copy. Missense variants: 296 observed, 337.17 expected, observed/expected ratio (o/e) 0.88, 90% interval 0.8 to 0.97. Synonymous variants: 134 observed, 121.58 expected, observed/expected ratio (o/e) 1.1, 90% interval 0.96 to 1.27.
Homologues: Orthologues: chimpanzee ATPAF1 (99% identical), macaque ATPAF1 (98% identical), rabbit ATPAF1 (91% identical), dog ATPAF1 (90% identical), mouse Atpaf1 (90% identical), rat Atpaf1 (89% identical), guinea pig ATPAF1 (88% identical), pig ATPAF1 (87% identical), tropical clawed frog atpaf1 (56% identical), zebrafish atpaf1 (53% identical), Drosophila melanogaster CG10340 (28% identical).
Diseases named in the same sentence as ATPAF1 in open-access papers:
ATPAF1 is named in the same sentence as 7 diseases in open-access papers, as found by Europe PMC text mining. Sharing a sentence is not in itself a finding about the gene and the disease. The quoted sentences say what the papers report.
prostate carcinoma (2 papers, 2014 to 2016). A carcinoma that arises from epithelial cells of the prostate gland. "Using this approach, the RIS were identified near a known prostate cancer gene PTRF as well as other genes that were not previously implicated in prostate cancer including ATPAF1, GCOM1, MEX3D, and TRPM4." (PMID 27792127, 2016).
asthma (1 paper, 2023). "Human ATPAF1, which is similar to S. pombe Atp11, may be the gene responsible for children's asthma." (PMID 37859837, 2023).
autism (1 paper, 2021). Persistent deficits in social interaction and communication and interaction as well as a markedly restricted repertoire of activity and interest as well as repetitive patterns of behavior. "To further determine whether these predicted proteins were associated with ASD, we compared their corresponding genes with autism-related genes listed in the AutismKB and found that 55 genes were reported associated with ASD except TTC13, RARS, THOC5, and ATPAF1." (PMID 33716802, 2021).
mild cognitive impairment (1 paper, 2024). "Discussion: This study firstly revealed that mitochondrial dysfunction may be the common pathogenesis of sleep loss and mild cognitive impairment and identified ATPAF1 as a possible biomarker and therapeutic target involved in SD and MCI." (PMID 38694919, 2024). "In addition, analysis of the MCI datasets showed that the expression of ATPAF1 was significantly downregulated in both the training and validation sets, suggesting that this gene may play an important role in both cognitive impairment and sleep loss." (PMID 38694919, 2024). "Therefore, we investigated the biological role of ATPAF1 to explore its potential mechanism in the development of cognitive impairment induced by SD." (PMID 38694919, 2024).
cancer (2 papers, 2014 to 2025). A tumor composed of atypical neoplastic, often pleomorphic cells that invade other tissues. "During the identification of effective cancer predictive genes, We initially excluded ATPAF1 (associated with mitochondrial function) and ECHDC1 (involved in fatty acid oxidation) from our analysis because the expression levels of these functional genes are influenced by multiple factors." (PMID 40608007, 2025). "ATPAF1 is widely expressed in host tissues, but to our knowledge has never been specifically linked to cancer." (PMID 24885513, 2014).
ATPAF1 also shares sentences with these, for which no sentence is quoted: ovarian carcinoma (1 paper); tumor (1).